SARM1 (sterile alpha and TIR motif containing 1)
Diseases named in the same sentence as SARM1 in open-access papers (continued):
Sharing a sentence is not in itself a finding about the gene and the disease.
neurodegenerative disease (37 papers, 2017 to 2026). A disorder of the central nervous system characterized by gradual and progressive loss of neural tissue and neurologic function. "SARM1 plays a pivotal role in triggering the neurodegenerative processes that underlie peripheral neuropathies, traumatic brain injury, and neurodegenerative diseases." (PMID 40722912, 2025). "SARM1 has been implicated in various neurodegenerative diseases not only due to its ability to promote axonal degeneration but also because of its correlation with neuroinflammation." (PMID 40433385, 2025). "Activation of SARM1 NADase activity has also been reported to play a role in axon loss during neurodegenerative diseases." (PMID 37253984, 2024). "This had led to mutations affecting SARM1 activity being investigated for a role in neurodegenerative diseases." (PMID 34828382, 2021). "It is conceivable that the phosphorylation or enzymatic activity of SARM1 could be specifically targeted in order to regulate various types of neurodegenerative diseases caused by a wide range of stressors." (PMID 40722912, 2025). "The hypothesis that naturally-occurring SARM1 polymorphisms could disinhibit normal enzyme activity and predispose to degenerative disease led us to examine exome sequence data from several well-annotated studies of ALS." (PMID 34991663, 2022). "The discovery of single point mutations in SARM1 that confer constitutive NADase activity leading to degeneration of cultured neurons prompted us to postulate that rare human gain-of-function SARM1 variants might increase risk for neurodegenerative disease." (PMID 34991663, 2022). "It has been hypothesized that such mutations, affecting the enzymatic activity of NMNAT2 or SARM1, could be considered risk factors for neurodegenerative diseases (Coleman and Höke, 2020)." (PMID 34307460, 2021). "This dual role of SARM1 in both axon degeneration and regeneration indicates that inhibiting SARM1 can be a way to block axon loss making it a therapeutic candidate for drug development to slow or stop aberrant Wallerian degeneration in several neurodegenerative diseases." (PMID 34307460, 2021). "The SARM1 molecule is known for its significant role in the development of degenerative diseases, particularly neurodegenerative disorders, primarily due to its intrinsic activity of degrading NAD+, which is dependent on its TIR domain." (PMID 40433385, 2025). "Since SARM1 can be pharmacologically modulated, it presents promising opportunities for developing treatments for inflammatory and neurodegenerative diseases." (PMID 40433385, 2025). "Given the critical role of SARM1 in AxD-related neurodegenerative disease and the advancements in understanding its regulatory mechanisms, it is crucial to explore novel avenues of SARM1 modulation." (PMID 39809779, 2025). "Recent studies have shown that SARM1 plays a key role in nerve injury, degeneration, and neurodegenerative diseases." (PMID 41018229, 2025). "Recent studies have demonstrated that SARM1 plays a pivotal role in nerve injury, degenerative diseases, and neurodegenerative diseases." (PMID 41018229, 2025). "Stabilized versions of NMN, while able to raise NAD, are potentially dangerous alternatives in NAD depleted systems (such as in neurodegenerative diseases) given that high ratios of NMN to NAD trigger SARM1 activation and axon degeneration." (PMID 39048544, 2024). "Inhibitors of SARM1 NADase activity are currently under development for the treatment of neurodegenerative diseases (see the section on NAD-boosting strategies)." (PMID 37253984, 2024). "SARM1’s role in initiating axon damage has been well studied in various mouse models of other neurodegenerative diseases." (PMID 39402114, 2024). "Employing this dual biomarker strategy will significantly enhance research into SARM1 activity in neurodegenerative diseases and validate targets for SARM1 inhibitors in animal models and human studies." (PMID 39768167, 2024).
neurodegenerative disease (continued). "SARM1 has been identified as a critical mediator of axon degeneration in the nervous system following traumatic injury, as well as in various neurodegenerative diseases." (PMID 37253984, 2024). "At present, preclinical studies of SARM1 inhibitors and gene therapies targeting SARM1 for neurodegenerative diseases are still being conducted." (PMID 37639066, 2024). "Increasing demand for effective axon damage inhibitors will increase the development and testing of new reagents to inhibit SARM1 to test in neurodegenerative diseases with extensive axon damage such as MS." (PMID 39402114, 2024). "SARM1 has emerged as a promising axon-specific target for therapeutic intervention, and its function, regulation, structure, and role in neurodegenerative diseases have been extensively characterized in recent years." (PMID 37002660, 2024). "Neurodegenerative diseases, traumatic brain injuries, toxic neuropathy, and peripheral neuropathy increase SARM1 activity in knockout mice." (PMID 38400192, 2024). "In addition, with the increasing use of exome sequencing for genetic diagnosis of neurodegenerative disease, our specific results provide immediately clinically relevant information, as well as provide a methodology for assessing the likely pathogenicity of further SARM1 variants in patients." (PMID 34991663, 2022). "We believe this discovery has important implications for the potential efficacy of SARM1 inhibition in the many neurodegenerative diseases with prominent mitochondrial dysfunction." (PMID 36287202, 2022). "SARM1 is the central executioner of pathological axon degeneration, an early feature of many neurodegenerative diseases." (PMID 34779400, 2021). "NAD+-consuming enzymes, such as sirtuins, Parps, and SARM1, are also being investigated for their role in neurodegenerative diseases." (PMID 34828382, 2021). "The discovery of Sarm1 and other axon death signaling molecules warrants a reassessment of the role of axon degeneration pathways in neurodegenerative diseases." (PMID 30010873, 2018). "For Sarm1 to be a viable target for treatment of ALS or other late-onset neurodegenerative diseases this mechanism of programmed axon destruction must be maintained in aged neurons." (PMID 30010873, 2018). "The promotion of regulated axon destruction by Sarm1 presents an appealing target for the treatment of neurodegenerative diseases and injury where pronounced axon degeneration occurs." (PMID 30010873, 2018). "It is believed that SARM1 plays a protective role in degenerative diseases and may impact mitochondrial bioenergetics." (PMID 41018229, 2025). "Additionally, SARM1 is an important NAD hydrolase that is deeply investigated in neurodegenerative disease." (PMID 38966636, 2024). "Accordingly, our findings may be highly relevant for developing anti-SARM1 therapies to mitigate the devastating consequences of these neurodegenerative disease." (PMID 38124145, 2023). "SARM1 is considered a very interesting therapeutic target to limit axonal degeneration in many neurodegenerative diseases, and such approaches may also apply to T124M-CMT2J." (PMID 36350884, 2022). "The role of SARM1 in neurodegenerative disease has primarily been tested in the mouse." (PMID 36287202, 2022). "In total, these findings will aid efforts to therapeutically target SARM1 to treat neurodegenerative diseases as they improve our understanding of SARM1 activation and its role as a critical switch in the degenerative process resulting in catastrophic axonal fragmentation." (PMID 34184985, 2021). "These recent findings indicate that research into SARM1 and the role it plays in various neurodegenerative diseases could provide novel insights into disease progression and development." (PMID 34828382, 2021).
neurodegenerative disease (continued). "Finally, the findings of this study raise important questions as to what other neurodegenerative stresses can partially activate SARM1, to what extent they contribute to sporadic neurodegenerative diseases and, importantly, if early detection and intervention is possible in humans." (PMID 39352636, 2025). "Axonal damage in neurodegenerative diseases, including MS, involves multiple mechanisms, one of which is the upregulation of sterile alpha TIR motif-containing protein 1 (SARM1), an essential mediator of axon degeneration." (PMID 41062626, 2025). "Sterile alpha and Toll/interleukin-1 receptor motif containing 1 (SARM1), a nicotinamide adenine dinucleotide (NAD)-utilizing enzyme, mediates axon degeneration (AxD) in various neurodegenerative diseases." (PMID 39809779, 2025). "As such, this work identifies SARM1 inhibition as a therapeutic candidate for the treatment of CMT2A and other neurodegenerative diseases with prominent mitochondrial pathology." (PMID 36287202, 2022). "The deletion of SARM1 has also been reported to alleviate symptoms of Alzheimer’s disease, Parkinson’s disease, and ALS, suggesting that it may be effective in treating neurodegenerative diseases." (PMID 40722912, 2025). "SARM1 is a key activation protein in WD as a NAD+ hydrolase; SARM1 inhibitors and NAD+ metabolism modulators are both molecular targets of interest in drug development for neurodegenerative diseases." (PMID 39381383, 2024). "Hence, SARM1 inhibition is a compelling therapeutic candidate for the treatment of CMT2A and, potentially, the many other neurodegenerative diseases characterized by mitochondrial dysfunction." (PMID 36287202, 2022). "Some TIR domains (including the TIR domain in SARM1) may therefore work together additively or synergistically for NAD+ cleavage in nerve and immune systems in response to several pathological settings related to not only degenerative diseases but also pathogen-related inflammatory diseases." (PMID 37725528, 2023). "SARM1, also known as SAMD2, plays an important role in neurodegenerative diseases, but its role in tumors has not been reported." (PMID 32428870, 2020). "Similarly, SARM1 inhibition through newly developed small molecule inhibitors are strong neuroprotective candidates but are reliant on large pools of NAD38, which are absent during the neurodegenerative disease cascades." (PMID 39048544, 2024).
infection (26 papers, 2010 to 2025). The state of being infected such as from the introduction of a foreign agent such as serum, vaccine, antigenic substance or organism. "In mouse CNS myelinating cocultures, loss of Sarm1 protects neuronal somas against infection and cell death." (PMID 37091921, 2023). "Surprisingly, although NAD+ depletion has been suggested to make SARM1 activation more likely we found no clear evidence of any additional depletion of NAD+ under conditions (ZIKV-infection) where SARM1 contributes to axon loss." (PMID 35493328, 2022). "The NADase activity of TIR domains was first characterized for the mammalian sterile α and TIR motif-containing 1 (SARM1), and SARM1 NADase activity was shown to promote neuronal death by NAD+ depletion in cases of neuronal injury or infection." (PMID 39172026, 2024). "In contrast, there was prolonged survival of neuronal processes in Sarm1 null cultures, accompanied by increased infection and death of neuronal somas." (PMID 35493328, 2022). "The role of SARM1 in infections has been conclusively established to restrict West Nile virus infection." (PMID 35947948, 2022). "As previously, Sarm1 wild type neuronal soma were relatively refractory to infection, but glial cell infection was accompanied by progressive degeneration of neuronal processes." (PMID 35493328, 2022). "Together, these data suggest that SARM1-dependent degeneration of neuronal processes limits infection and death of neuronal somas." (PMID 35493328, 2022). "In pigs, the SARM1 orthologue negatively regulates NF-κB in a TRIF-dependent pathway during the infection with porcine reproductive and respiratory syndrome virus." (PMID 34307460, 2021). "Melioidosis, the infection of macrophages arising from the bacteria Burkholderia pseudomallei, is dependent on SARM-1." (PMID 34485381, 2021). "The data showed that the overexpression of miR-144-3p failed to downregulate and significantly upregulated the mRNA expression of TNIP3 and SARM1 in human MDMs before and after infection with Mabc or Mmass." (PMID 33473145, 2021). "Consistently, in mice, SARM1 expression has been shown to increase during the infection of macrophages with Burkholderia pseudomallei, leading to the inhibition of TRIF and hence decreasing IFNβ (β interferon) production." (PMID 34307460, 2021). "In horseshoe crabs, Carcinoscorpius rotundicauda, the SARM1 orthologue is shown to downregulate TRIF-dependent NF-κB activation during the infection with Pseudomonas aeruginosa." (PMID 34307460, 2021). "A recently identified NAD+ degrading enzyme with relevance to infection, SARM-1 is mainly expressed in neurons." (PMID 34485381, 2021). "Infection of Sarm1FLAG cells confirmed that Kp52145 increased the expression of SARM1." (PMID 35947948, 2022). "We labeled the TIR-1/SARM1 protein with a fluorescent tag at its genomic locus and demonstrated that TIR-1/SARM1 forms visible puncta within the intestine in response to physiologic stimuli, including both pathogen infection and cholesterol deficiency." (PMID 35098926, 2022). "As some neurotropic viruses use microtubule-dependent axon transport to reach the neuronal soma, the changes observed in microtubule staining at 24 hpi led us to ask whether SARM1-dependent mechanisms might limit infection of neuronal somas." (PMID 35493328, 2022). "Whilst lyssavirus does not induce apoptosis in infected neurons, it has been shown that neurons activate a selective and compartmentalized SARM-1-mediated degeneration of their axons and dendrites in response to infection with different field strains of lyssavirus." (PMID 35004351, 2021). "This suggests SARM-1 could link infection and neuronal injury by incorporating NAD+ availability in this role." (PMID 34485381, 2021). "The SARM1-dependent loss of axons and dendrites with absent or delayed neuronal cell death following infection by bunyavirus or rabies virus could thus provide an intriguing link between innate immunity and axon degeneration mechanisms." (PMID 35493328, 2022).
infection (continued). "Full complementation was observed for the expression levels of TRIM39, SARM1, SLC25A26, NDUFA8 and DTYMK by infection with C∆tbcm, which showed similar trends as wild-type BCG infection." (PMID 38110948, 2023). "Multimerization of TIR-1/SARM1 and its intrinsic NAD+ glycohydrolase activity are required for activation of the p38 PMK-1 innate immune pathway during pathogen infection." (PMID 35098926, 2022). "Cholesterol scarcity increases p38 PMK-1 phosphorylation, primes immune effector induction in a manner that requires TIR-1/SARM1 oligomerization and its intrinsic NAD+ glycohydrolase activity, and reduces pathogen accumulation in the intestine during a subsequent infection." (PMID 35098926, 2022). "Other functions of SARM1, such as hydrolyzing NADP+ and performing base exchange reactions, as well as the immunity-related activities, may play a role in the early stages of infection." (PMID 37002660, 2024). "Absence of SARM1 resulted in enhanced levels of processed GSDMD upon infection." (PMID 35947948, 2022). "Thus, the significant increase in infection and death of neuronal somas in SARM1-depleted cultures (with delayed degeneration of neuronal processes) suggests that ZIKV can be transported in this way too and that SARM1-dependent degeneration of neuronal processes limits its spread to neuronal somas." (PMID 35493328, 2022). "To investigate any role SARM1 may play in ZIKV-induced death of neuronal processes, we infected CNS myelinating spinal cord cultures from wild type mice, or Sarm1 heterozygous or homozygous null mice on a type I interferon receptor (Ifnar1) null background; the last to facilitate infection." (PMID 35493328, 2022).
peripheral neuropathy (22 papers, 2018 to 2025). A disorder affecting the peripheral nervous system. "Loss of SARM1 has been shown to protect mice from peripheral neuropathies and TBI-induced axon loss, although there is still a debate on the contribution of SARM1 to ALS." (PMID 34307460, 2021). "Notably, inhibition of SARM1 also protects axons from fragmentation in multiple peripheral neuropathies caused by chemotherapeutic and metabolic factors." (PMID 39335636, 2024). "Because the pathogenic effects of SARM1 activity are not limited to motoneurons, we also hypothesize that rare SARM1 variation may raise risk for other neurodegenerative conditions such as peripheral neuropathies." (PMID 34991663, 2022). "A limitation of this study is that it is unclear to what extent the in vivo improvement effect of carnosol on peripheral neuropathy depends on SARM1 inhibition." (PMID 40722912, 2025). "It has been reported that the symptoms of VCR-induced peripheral neuropathy are significantly reduced in SARM1 knockout mice." (PMID 40722912, 2025). "Genetic deletion of SARM1 is profoundly protective in rodent models of traumatic nerve injury, traumatic brain injury, peripheral neuropathy, and chemotherapy-induced peripheral neuropathy, as well as slowly progressive axonopathies including CMT2A." (PMID 38334594, 2024). "Decreased levels of NMNAT2, triggered by physical injury or pathological stimuli, activate SARM1, leading to axonal degeneration and the onset of neurodegenerative diseases and peripheral neuropathy." (PMID 38275737, 2024). "Inhibition of SARM1 represents an attractive therapeutic target for treating various pathologies of axon degeneration, including peripheral neuropathy, traumatic brain injury, and neurodegenerative disorders." (PMID 38275737, 2024). "For example, in paclitaxel-induced peripheral neuropathy, SARM1 is activated to produce cADPR, resulting in the increase of calcium and AxD17." (PMID 36550129, 2022). "In paclitaxel-induced peripheral neuropathy, SARM1 is activated to produce cADPR, which in turn elevates cellular calcium, resulting in AxD17." (PMID 36550129, 2022). "Sarm1 was later shown to mediate other types of axon degeneration such as in traumatic brain injury and peripheral neuropathy." (PMID 35285800, 2022). "Vincristine (VCR)-induced AxD in peripheral neuropathy is a common side effect of chemotherapy and is thought to be due to SARM1-activation." (PMID 33944777, 2021). "For example, mice lacking Sarm1 have improved functional outcomes as well as attenuated axonal injury following mild traumatic brain injury, while deletion of Sarm1 prevents chemotherapy induced peripheral neuropathy." (PMID 31661035, 2019). "Indeed, carnosol alleviates the symptoms of peripheral neuropathy through not only SARM1 inhibition, but also through an antioxidant effect via NRF2 activation." (PMID 40722912, 2025). "Recently, the gene for serum sterile alpha and toll/interleukin receptor motif-containing protein 1 (SARM1), which may contribute to the pathogenesis of Wallerian degeneration, was discovered in mice models of peripheral neuropathy." (PMID 38400192, 2024). "Although axon degeneration is rescued by SARM1 deletion in some models (e.g. chemotherapy-induced peripheral neuropathy; TDP43-linked ALS), it is not in others (SOD1 mouse model of ALS; and optic nerve crush)." (PMID 36778383, 2024). "Considering its potential, SARM1 could be a promising target for the development of therapeutic interventions aimed at improving the treatment of peripheral neuropathies." (PMID 38400192, 2024). "Sarm1 is essential for Wallerian degeneration in flies and mammals and has a role in selected additional degeneration models such as traumatic brain injury and peripheral neuropathy." (PMID 35285800, 2022).